IL10 (interleukin 10)
Diseases named in the same sentence as IL10 in open-access papers (continued):
Sharing a sentence is not in itself a finding about the gene and the disease.
viral infection (411 papers, 2005 to 2026). "Virus infection induced dysregulation of the proinflammatory cytokine response such as overproduction of immunosuppressive IL-10, is generally believed to play a major role in predisposing to secondary bacterial infection." (PMID 39858958, 2025). "Collectively, these data demonstrate that short-term HFD can have an overall detrimental effect on NK cell functions in a viral infection that involves the disruption of mitochondrial activity and is associated with increases in the inhibitory cytokine IL-10." (PMID 40352719, 2025). "This review offers valuable perspectives on the role of IL-10 in mediating immunosuppression caused by viral infections, thereby identifying potential therapeutic targets for addressing IL-10-mediated immunosuppressive effects in viral pathogenesis." (PMID 41156600, 2025). "Elevated levels of IL-10 are commonly observed in CHB viral infections and are associated with T cell impairment, as neutralizing IL-10 can boost T cell function and improve viral control." (PMID 39065812, 2024). "Our results have also shown that susceptibility to SARS-CoV-2 infection was associated with all the genotypes of IL-10 -592 C > A polymorphism, with the C allele favoring protection against infection which was consistent with different viral infections." (PMID 38287362, 2024). "Polymorphisms in the interleukin-10 (IL10) gene have been linked to the severity of the patients infected with the viral infections." (PMID 36882862, 2023). "When perforin-deficient mice are infected with MCMV, the viral infection persists, and NK cells secrete IL-10 to inhibit the function of CD8+ T cells." (PMID 38022497, 2023). "During the course of lymphocytic choriomeningitis virus (LCMV) infection, NK cells can suppress CD8+ T cell responses by secreting IL-10, thus causing suboptimal control of viral infection." (PMID 38022497, 2023). "This is probably due to the immunosuppressive effect of highly expressed IL-10, which is caused by viral infection." (PMID 36541788, 2023). "Previous studies have showed that IL-10 can suppress viral infections, including the diseases caused by HSV, alpha virus, HIV, RSV, HCV, Japanese encephalitis virus, influenza virus, vaccinia virus, dengue virus, and coronavirus." (PMID 36914565, 2023). "IL-10 was positively associated with immune evasion and the persistence of viral infections such as HCV, HIV and EBV." (PMID 36233146, 2022). "In bacterial infections, it is known to enhance the susceptibility of lung tissue to pathogens; in viral infections, the IL-10 pathway dampens NKT responses." (PMID 36430621, 2022). "IL10 is well known as an important anti-inflammatory cytokine, which can prevent excessive tissue damage caused by bacterial and viral infections as well as pro-inflammatory responses." (PMID 34827211, 2021). "In another report, IL-6 has been associated with IL-10 in viral infection, showing that IL-6 regulates the maturation of Treg cells and that IL-6 depletion also causes significant ablation of IL-10 in the lungs after RSV infection in an animal model." (PMID 33815363, 2021). "Bregs producing IL-10 has been shown to exert pleiotropic unfavorable effects in the course of virus infections and some of them have been linked to severe disease pathogenesis." (PMID 34293057, 2021). "IL‐10+ regulatory T cells are symptomatic of many unresolved viral infections and are associated with long‐term persistence." (PMID 33209300, 2020). "Virus infection caused significantly increased IL-1β and IL-6 as well as significantly decreased IL-10 in the control infected group (P < 0.01)." (PMID 31551774, 2019). "Having successfully generated an NK cell-specific Il10-deficient mouse model, we decided to investigate the role of NK cell-derived IL-10 during acute viral infection." (PMID 31803193, 2019). "The early events that facilitate viral persistence in chronic viral infections have been linked to the activity of the immunoregulatory cytokine IL-10." (PMID 30863397, 2019).
viral infection (continued). "A detailed immunological investigation of these patients revealed impaired responses to type I IFN, IL-10, IL-12 and IL-23, which are associated with increased susceptibility to mycobacterial and/or viral infections." (PMID 29725107, 2018). "Removal of the IL-10 “brake” on Th responses can lead to immunopathology following viral infection as illustrated by the increased neurologic disease detected in IL-10-deficient mice during fatal alphavirus encephalomyelitis." (PMID 28316998, 2017). "It is thus apparent that chronic viral infections often use the regulatory role of IL-10 on T cells and APC to cause T cell exhaustion and deactivate antiviral T cell immunity." (PMID 28316998, 2017). "In regards to the association with viral infection, Herpesvirus-associated meningoencephalitis displays an IL-10-modulated inflammatory profile, whereas Enterovirus is especially characterized by the IL-17/IL-12 diad inflammatory profile." (PMID 26286516, 2015). "IL-10 is also implicated in the development of secondary bacterial infections following viral infections or trauma, conditions associated with TLR-9 activation." (PMID 26218271, 2015). "We also measured serum levels of CXCL10, an epithelial chemokine, and IL-10, since these two cytokines were associated with a poor outcome during viral infection and particularly SARS-CoV acute respiratory infection." (PMID 24551142, 2014). "Higher IL-10 levels are associated with impaired immunity against bacterial, mycobacterial and viral infections." (PMID 23374857, 2013). "PD-1 expression on T lymphocytes is typically associated with a chronic virus infection and T cell exhaustion, as well as regulated IL-10 production." (PMID 23620814, 2013). "IL-10 is known to suppress inflammation and associated tissue damage as well as lead to chronic or more persistent virus infections." (PMID 23620814, 2013). "Patients with more severe clinical disease have been shown to have higher serum IL-10 levels and IL-10 has also been shown to be associated with poorer disease outcome in other viral infections." (PMID 24040431, 2013). "The IL-10 –819*T and –592*A alleles have now been linked to other viral infections such as hepatitis B virus (HBV) and Herpes Zoster (HZ) and human immunodeficiency virus (HIV)." (PMID 24470873, 2013). "IL-10 promoter polymorphisms with outcomes of viral infections such as HIV and HBV have been reported." (PMID 24470873, 2013). "Serum IL-10 has also been shown to be associated with severe disease in other acute viral infections such as influenza." (PMID 23883139, 2013). "IL-10 levels have also been shown to be associated with severe disease in patients with other virus infections such as influenza and related to neurological complications." (PMID 23209731, 2012). "We also measured IL-10 production because this regulatory cytokine is associated with poor control of persistent viral infections." (PMID 23144619, 2012). "IL-10 has been implicated in the pathogenesis of both autoimmune as well as viral diseases, and the fact that many viruses carry IL-10 orthologs speaks to the potency of IL-10 in manipulating the host immune system." (PMID 18389062, 2008). "- AR complete TYK2 deficiency (with or without TYK2 expression): Characterized by MSMD (and more rarely tuberculosis) and/or viral diseases due to an impaired response to IL-12, IL-23 (poor IFN-γ underlies mycobacterial diseases), IFN-α (viral diseases), and IL-10 signaling." (PMID 41438753, 2025). "For example, CD56bright NK cells produce immunoregulatory cytokines, such as IFN-γ, TNF-α, and IL-10, that may support viral clearance and reduce inflammation associated with severe viral infections." (PMID 40411624, 2025). "IL-10 could facilitate innate immune responses to reduce the damage caused by bacterial and viral infections." (PMID 38696304, 2024).
viral infection (continued). "However, in chronic virus infections (such as HCV, HBV, and HIV), elevated IL-10 levels during the acute phase have been linked to disease progression and persistent virus infections, mainly caused by T cell dysregulation." (PMID 37235332, 2023). "Meanwhile, the mRNA expression levels of IL-10 showed a trend of decreasing and then increasing, which might have been caused by the complex role of IL-10 in acute viral infection." (PMID 35624806, 2022). "Previously, a low ratio between IFNγ and IL10 has been associated with viral infection." (PMID 36293090, 2022). "In conclusion, high levels of IL-10 may be associated with poor prognosis of viral infection-associated liver diseases, while the effect of IL-10 on HBV-ACLF remains to be studied." (PMID 36117587, 2022). "We also probed for IL-10, a cytokine linked to the functional capacity of Tregs, in line with reports suggesting a role for Tfr cell-derived IL-10 in the modulation of GC responses in acute viral infection." (PMID 34177929, 2021). "Besides the IFN family, the critical role of IL-10 was found during an emerging inflammation caused by a viral infection." (PMID 34484241, 2021). "Through the analysis of the experiments, we speculate that the decrease in peripheral blood lymphocytes and the increase in IL-10 levels may be due to the imbalance of cytokines and the migration of lymphocytes caused by viral infection." (PMID 34960654, 2021). "Exhaustion of CD8+ T cells and increased IL-10 production is well-known in chronic viral infections but mechanisms leading to loss of their cytotoxic capabilities and consequent exhaustion remain unclear." (PMID 32210950, 2020). "Overproduction of TNF-alpha, IL-1, IL-6 and IL-10 hallmark of viral infection.Investigated inflammatory profiles of patients infected with SARS in Hong Kong hospital.Use of corticosteroids significantly reduced IL-8, MCP-1 and IP-10 concentrations from 5-8 days after treatment." (PMID 32256705, 2020). "Thus, IL-10 prevents excessive tissue damage caused by bacterial and viral infections as well as regulates and represses proinflammatory responses." (PMID 31244763, 2019). "In viral infections, IL-10 levels are associated with diminished T-cell activation, which may already start to occur rapidly after infection." (PMID 31233500, 2019). "In contrast, based on earlier reports, IL10 genetic polymorphisms may associate with resistance to some viral infections." (PMID 30487959, 2018). "Importantly, salivary gland IL-10+ T cells expressed high levels of the co-stimulatory molecule ICOS that has previously been implicated in the development of IL-10-secreting CD4+ T cells during viral infection." (PMID 27926930, 2016). "The IL10 gene has more than 27 polymorphic sites associated with SNPs that result in the differential production and expression of the cytokine, autoimmune and inflammatory diseases, bacterial and viral infections, and human malaria." (PMID 27999453, 2016). "The presence of the suppressor cytokine IL-10, produced by MØs during a virus infection, by downregulating mediators associated with type 1 antiviral immune responses, could delay virus eradication and even allow viral persistence." (PMID 25430775, 2015). "Although IL-27 acts to induce IL-10 during primary virus infection, CD8+ T cells have a loss of responsiveness to IL-27 during recall response related to an attenuation of the glycoprotein 130 cytokine receptor, resulting in down-regulation of IL-10 production." (PMID 25651926, 2015). "Together, these data suggest that IL-10 mediated suppression of lung pathology following viral infection may come at the cost of enhanced susceptibility to secondary bacterial super-infection." (PMID 25651926, 2015). "It is not possible to say at this stage whether the observed induction of IL-10 is a cause or consequence of the pathogenic effect of virus infection in these animals." (PMID 24559207, 2014).
viral infection (continued). "High serum IL-10 levels have been shown to be associated with a worse outcome in many viral infections including influenza and hepatitis B, while in some viral infections such as in Japanese Encephalitis virus infection high IL-10 levels were shown to be associated with a favorable outcome." (PMID 24040431, 2013). "The results may further underlie in part known exacerbation of IL-10/T helper-2-related allergic disorders by stress and viral infection." (PMID 23667643, 2013). "IL-10 disrupts virus-specific T cell responses and causes persistence of viral infection." (PMID 24086341, 2013). "Our results on the cooperation of DEX and virus on IL-10 production may in part explain the previous observation that mental/physical stress increases susceptibility to viral infection and tendency to exacerbate/prolong its disease course." (PMID 23667643, 2013). "The mechanisms responsible for the observed associations between IL-10 polymorphisms and viral infection are still unclear, but appear to be related to the level of IL-10 gene expression and the corresponding effects on the TH1 response and modulation of inflammation." (PMID 22986179, 2012). "To decisively determine the causal role of IL-10 in generating T cell anergy during persistent viral infections, and to avoid the vagaries of multiple injections of heterospecific neutralizing antibodies, we attempted to persistently infect IL-10 deficient mice." (PMID 17570849, 2007). "However, in some cases, it may promote the survival of pathogens and the immune escape of tumors, and elevated IL-10 may be associated with the activity of viral infections." (PMID 39968105, 2025). "This has been described for HCV and HIV infections in which high IL-10 levels in the early/acute phase are associated with progression to persistence, which suggests that this is an evolutionarily conserved mechanism in persistent viral infections with clinical relevance." (PMID 28316998, 2017). "Since low levels of IL-10 increase resistance and high levels increase susceptibility, the high expression of IL-10 may help us to understand the increase in susceptibility to concurrent or secondary bacterial or viral infections post REV-A infection." (PMID 24358317, 2013). "IL-10 has strong anti-inflammatory and immunosuppressive effects, which affects viral infections in a dual manner." (PMID 41156600, 2025). "A strong significant correlation was found between the detected viral infection and IL-10 (r = 0.546; p < 0.001)." (PMID 40430746, 2025). "The serum IL-10 levels in the group of children infected with another virus were slightly lower than those in the group with an undetected type of virus infection." (PMID 40430746, 2025). "IFN-γ is known for its role in the immune response against viral infections and its ability to activate macrophages, while IL-10 is a crucial anti-inflammatory cytokine that helps regulate immune responses and limit excessive inflammation." (PMID 39941091, 2025). "The next step was performing a classical ELISA for representative cytokines important for viral infection—IL-4, IL-5, IL-6, IL-10, IL-17, and TNF alpha." (PMID 40358160, 2025). "Among the cytokines secreted during viral infection, IL-10 is an important immune regulatory factor, and its role is usually linked to the attenuation of inflammatory conditions." (PMID 40002722, 2025). "Prior research has demonstrated that targeting immune regulators such as IL10 can modulate viral infection outcomes." (PMID 40430433, 2025). "In chronic viral infections, the sustained IL-10 production can lead to decreased IFN-γ production from virus-specific T cells, thereby contributing to viral persistence." (PMID 41156600, 2025). "Variance analysis of IL-10 serum levels revealed statistically significant differences among the patient groups depending on the type of viral infection, concerning respiratory failure (p = 0.005) and wheezing severity (p = 0.017)." (PMID 40430746, 2025).
viral infection (continued). "This review aims to recapitulate the cellular sources of IL-10, the mechanisms of its production, and the molecular pathways involved in viral infection-driven immunosuppression." (PMID 41156600, 2025). "By summarizing current knowledge on IL-10’s role in viral infections, this review offers a thorough insight into its immunosuppressive mechanisms and their therapeutic potential, paving the way for innovative treatment strategies in viral diseases." (PMID 41156600, 2025). "Overall, TIGIT appears to diminish T cell effector function, either through the induction of IL-10 production or via other mechanisms, particularly in the context of persistent viral infections." (PMID 40872232, 2025). "This review aims to elucidate the mechanisms through which IL-10 mediates immunosuppression in viral infections and to explore the implications of these mechanisms for therapeutic intervention." (PMID 41156600, 2025). "IL-10, a key anti-inflammatory cytokine, plays a complex role in regulating immune homeostasis during viral infections." (PMID 40678119, 2025). "Interleukin-10 (IL-10) is a key cytokine with a profound impact on modulating immune responses, particularly during viral infections." (PMID 41156600, 2025). "TIGIT restricts immune-mediated tissue damage during acute virus infection in an IL-10-dependent manner during acute LCMV and influenza virus infection." (PMID 41156600, 2025). "Cytotoxic T cells (CD8+) also become an important source of IL-10 during hypoxia and viral infections." (PMID 40283387, 2025). "In the context of viral infections, IL-10 exerts anti-inflammatory via reducing the production of pro-inflammatory cytokines and chemokines, including TNF-α, IL-1β, IL-6, and IL-12, etc.." (PMID 41156600, 2025). "The elevated IL-10 level represents a notable feature following numerous viral infections, such as SARS-CoV-2, influenza A virus, LCMV, HIV, porcine reproductive and respiratory syndrome virus (PRRSV), porcine circovirus type 2 (PCV2), FMDV, and others." (PMID 41156600, 2025). "In chronic viral infection, however, prolonged antigenic stimulation and continuous engagement of Toll-like receptors can reshape IL10 transcriptional control." (PMID 41465112, 2025). "Glycoprotein indicators such as IL-1β, IL-8, IL-10, and IgM regulate fish immune response, represent innate immunity, and alter viral disease response." (PMID 41001068, 2025). "Consistent with this suggestion that the TT genotype provides better protection against viral infections, preferably CMV, the Allele-2 group had higher circulating IFN-β levels and an increased IFN-β/IL-10 ratio than other groups during the study periods." (PMID 40872872, 2025). "The key scientific concepts outlined in this review include the mechanisms of IL-10 production and its varied impacts on the immune response during viral infections." (PMID 41156600, 2025). "It is noted that these viral infections/co-infections induce T cells exhaustion, accompanied by a high level of IL-10." (PMID 41156600, 2025). "Conversely, the presence of anti-inflammatory cytokines such as IL-10 leads to compromised immune clearance and persistent infectious effects during acute viral infection." (PMID 39457019, 2024). "Of particular interest in the context of viral infections was the observation of increased IL-10 secretion by ILC2s upon IFN-β stimulation." (PMID 39038044, 2024). "Several lines of evidence suggest that blocking IL-10 signaling facilitates clearance of viral infection and prevents tumor growth in animal models." (PMID 38846955, 2024). "The regulatory functions of IL-27 in the setting of viral infection involves both IL-10 dependent and independent mechanisms." (PMID 38966644, 2024). "IL-10 functions are mainly immunosuppressive, as described in bacterial and viral infections, and cancer diseases." (PMID 38646609, 2024).